PIR (pirin)
Diseases named in the same sentence as PIR in open-access papers (continued):
Sharing a sentence is not in itself a finding about the gene and the disease.
skin ulcerations (1 paper, 2013). "Due to skin ulcerations, PIR B-/- and PD-L1-/- mice were unable to be maintained past 10 mo of age." (PMID 24040397, 2013).
Stroke (1 paper, 2023). Sudden impairment of blood flow to a part of the brain due to occlusion or rupture of an artery to the brain. "Along with its role in the regulation of NF-κB activity, Pirin signaling appears to play a role in cytoskeleton remodeling, metastasis and invasion of tumors, platelet aggregation, and stroke." (PMID 38033031, 2023).
testicular cancer (1 paper, 2023). A primary or metastatic malignant neoplasm that affects the testis. "A recent report suggested that piR-36249 regulates testicular cancer progression by engaging with DHX36 to regulate OAS2." (PMID 37662498, 2023).
transient ischemic attack (1 paper, 2023). A brief attack (from a few minutes to an hour) of cerebral dysfunction of vascular origin, with no persistent neurological deficit. "Transient ischemic attacks (TIAs) were enriched for Pirin signaling." (PMID 38033031, 2023).
tumor (75 papers, 2010 to 2026). "Several studies have demonstrated associations between piR-823 expression and tumor-node-metastasis (TNM) stage, histological type, cancer progression, and overall survival in various cancer types." (PMID 41596471, 2026). "From our five signatures, piR‐hsa‐2499988 related to 5S rRNA is identified as downregulated in tumour samples, indicating the association with potential inhibition mechanism of cancer cell proliferation in tissues." (PMID 40714929, 2025). "In neuroblastoma, piR-39980 expression correlated with the resistance to doxorubicin, its upregulation promoted tumor progression and its inhibition caused induction of senescence." (PMID 38303021, 2024). "Tissue expression of piR-823 was significantly associated with poorly differentiated tumor tissue and stage III and IV." (PMID 38031146, 2023). "Several reports have implicated pirin as an important factor in cancer cell proliferation, migration, and tumour progression." (PMID 35204145, 2022). "Loss- and gain-of-function assays showed that piR-57125 act as a tumor suppressor gene that played an important role in ccRCC metastasis." (PMID 34732692, 2021). "These genes had functions in key tumor suppressive pathways and their expression was associated with piR-1245 expression." (PMID 34193172, 2021). "The higher expression of piR-30924 and piR-38756 as well as the lower expression of piR-57125 in metastatic primary tumors were significantly associated with tumor recurrence and OS." (PMID 31399034, 2019). "Notwithstanding its overexpression in cancer, we discovered that piR-1245 is a promising cancer biomarker, since its overexpression correlated with known risk clinicopathological features such as tumor depth, tumor differentiation and metastasis." (PMID 29382334, 2018). "In order to evaluate the role of pirin in tumours associated with HPV, we determined the levels of biomarkers related to EMT using a specific siRNA for PIR silencing." (PMID 29118270, 2017). "The higher expression of piR-30924 and piR-38756 as well as the lower expression of piR-57125 in metastatic primary tumors were significantly associated with tumor recurrence and overall survival." (PMID 26071182, 2015). "piR-651 may act as a tumor suppressor since patients with low piR-651 levels had shorter OS, associated with worse response to first-line treatment." (PMID 27329591, 2016). "Several studies suggest that a deregulation of PIR expression may be associated to tumor progression." (PMID 20089166, 2010). "Conversely, piR-28846 is downregulated in OC, suppresses tumor growth in vitro, and exhibits therapeutic potential in xenograft and organoid models." (PMID 41596471, 2026). "In this study, we investigated the clinical and molecular significance of piR-823 in OC and explored its potential regulatory role in tumor progression through a proposed epigenetic axis involving PIWIL1, DNMT3B, and CDH1." (PMID 41596471, 2026). "This multicenter study identifies piR-hsa-8393202 and piR-hsa-8429916 as novel, tumor-derived circulating biomarkers for the early detection of LUAD and molecular classification of IPNs." (PMID 41319254, 2025). "In contrast to synthetic compounds or ASOs, piR-26441 functions as a natural tumor suppressor in humans." (PMID 39827178, 2025). "Previous studies have suggested that genes such as BCAR1 and PIR in tumor cells are considered oncogenic factors, with their increased expression in tumor tissues being closely associated with poor prognosis." (PMID 41430038, 2025). "PIR is upregulated in CRC tissues, correlating with reduced ferroptosis sensitivity and enhanced tumor growth, whereas PIR loss restricts CRC progression in vivo and in vitro." (PMID 41400081, 2025). "In summary, this study establishes piR-hsa-8393202 and piR-hsa-8429916 as robust, tumor-derived, and functionally relevant circulating biomarkers for LUAD detection and IPN stratification." (PMID 41319254, 2025).
tumor (continued). "piR-57125 upregulation suppressed metastasizing in vivo and the tumor suppressive effect was mediated by the downregulation of the CCL3 chemokine, which led to decreased activation of the AKT/ERK pathway." (PMID 38303021, 2024). "Third, administration of PIR inhibitor can significantly retard mice xenograft tumor growth of HCT116 cells." (PMID 38148593, 2024). "Consistently, intravenous administration of PIR inhibitor CCG‐1423 also effectively inhibited tumor formation." (PMID 38148593, 2024). "Our tumor tissue microarray IHC data and the open access clinical dataset indicate that PIR is upregulated in CRC at both protein and mRNA levels." (PMID 38148593, 2024). "To further validate the enhanced resistance to androgen deprivation exerted by piR-4447944 in PCa cells, we assessed the impact of forced piR-4447944 expression in castrated SCID mice bearing xenograft tumor derived from LNCaP cells." (PMID 38993562, 2024). "So, role of Pirin in cancers appears to be more centered to migration and invasion of tumor cells, instead of growth and initiation." (PMID 38033031, 2023). "In BC, piR-2158 is downregulated in CSCs; it was demonstrated that the overexpression of piR-2158 prevents mammary gland tumorigenesis via regulating CSCs and tumor angiogenesis." (PMID 37568728, 2023). "Knockdown of PIR in MCF7 and MDA-MB-231 cell lines caused a dramatic decrease in cell proliferation and xenograft tumor growth in mice by activating E2F1 and its target genes." (PMID 37647033, 2023). "This study provides mechanistic insights into how Pirin’s conformational alterations regulate its interaction with key inflammatory regulators, as well as its function in tumor invasion, and other metabolic and neuropathological complications." (PMID 38033031, 2023). "Having assessed the capacity of Pirin to regulate basic tumor-related processes like proliferation, and in order to reveal the molecular mechanisms regulated by this protein, we performed a RNA-seq analysis." (PMID 37308689, 2023). "Based on Spearman and Kendall rank correlation test, the folds change of pirin expression in tumour vs. the corresponding normal tissues correlated with the fold change of NQO1 expression (p = 0.001271 and p = 0.0008092)." (PMID 35204145, 2022). "Curiously, piR-162725 was also upregulated in both tumour cell lines compared to pre-malignant IPMN (Log2 fold change = 12.13; adjusted p-value = 0.0014)." (PMID 36555927, 2022). "The mRNA levels for NQO1 were increased in 25/48 tumours and decreased in the same two tumour samples, which also had lower pirin expression." (PMID 35204145, 2022). "In contrast, piR-168112 expression was lower in tumour cell lines after PIWIL3 silencing than in the same cell lines transfected with scramble (Log2 fold change = −25.58; adjusted p-value = 6.32 × 10−10)." (PMID 36555927, 2022). "In contrast, the down-regulation of piR-001773, as well as piR-017184, significantly inhibits tumor growth." (PMID 36733811, 2022). "In contrast, the expression of piR-168112 and piR-162725 was higher in tumour cell lines compared to the untransformed cell line, which was in accordance with the NGS analyses." (PMID 36555927, 2022). "Together, these data strongly suggest that the overexpression of pirin in the tumour tissues is dependent on Nrf2." (PMID 35204145, 2022). "The HCT116 cells xenograft model in nude mice also showed that piR-823 inhibition impair tumor growth." (PMID 35581181, 2022). "The overexpression of piR-30924 as well as piR-38756 while a low expression of piR-57125 among metastatic primary tumors was found considerably correlated to tumor recurrence and overall survival." (PMID 36733811, 2022). "Previous studies reported the overexpression of PIR in different neoplastic transformation and its role in the enhancement of tumor formation due to inducing the expression of Bcl3 by forming the ternary complex with proto-oncogenes Bcl3 and NF-kB." (PMID 34262943, 2021).
tumor (continued). "The regulation of DNMTs and APC by piR-823 were validated in the tumor samples from the xenograft model." (PMID 33791297, 2021). "Colorectal cancer tumor growth and metastasis was found to be enhanced by increased levels of oncogenic piR-1245 which is capable of binding and subsequently suppressing multiple tumor suppressors such as ATF3, DUSP1, and SESN2 by degradation of mRNA." (PMID 33673453, 2021). "Taken together, these results revealed that piR-57125 plays a tumor-suppressor role to inhibit ccRCC metastasis in vivo." (PMID 34732692, 2021). "Collectively, these results suggested that piR-19166 serves as a tumor suppresser in migration of PCa and a role of inhibitor for piR-19166 in the regulation of metastasis in PCa." (PMID 32881713, 2020). "They found that rs147061479 abolished the tumor-suppressive function of piR-598, instead conferring tumor growth-promoting properties." (PMID 33109195, 2020). "They found that piR-52200 and piR-34871 were up-regulated, while piR-46545 and piR-35127 were down-regulated in half of tested tumor tissues." (PMID 31890151, 2019). "piR-39980, a fibrosarcoma tumor suppressor, inhibits ribonucleoside-diphosphate reductase subunit M2 (RRM2) expression by binding to its 3′-UTR." (PMID 31399034, 2019). "piR-30188 suppresses tumor cell proliferation, invasion, and migration and promotes apoptosis by binding to OIP5-AS1." (PMID 31399034, 2019). "The TCGA datasets showed piR-1245 is significantly up-regulated in tumor tissues compared to normal tissues in different types of cancer." (PMID 29382334, 2018). "PiR-34871 and piR-52200 were significantly up-regulated in about 50–58% of tumor tissues, while piR-35127 and piR-46545 were down-regulated in about 50% of tumor tissues." (PMID 28423657, 2017). "Although our findings suggest specific HPV-dependent PIR overexpression, alterations in PIR expression have also been observed in various tumours under conditions of oxidative stress, especially in tobacco smoke-associated cancers." (PMID 29118270, 2017). "In vivo studies showed that the over-expression of piR-823 significantly inhibited tumor growth in a dose-dependent manner." (PMID 23965974, 2013). "Recent studies also highlighted that the PIWIL2 protein works in combination with piR-932 influencing the biological behavior of BCSCs through the methylation of Latexin (LXN) gene, coding for a tumor suppressor protein which reduces the risk of old stem cells transforming into cancer stem cells." (PMID 40951838, 2025). "Notably, only piR-hsa-8393202 and piR-hsa-8429916 displayed consistent upregulation across both tumor tissues and serum samples." (PMID 41319254, 2025). "Furthermore, to assess piR‐RCC's role in tumor metastasis in vivo, we orthotopically injected luciferase‐labeled ACHN RCC cells in nude mice." (PMID 40411401, 2025). "With a correlation found between the levels of piR-823 and both distant metastasis and tumor node metastasis (TNM) indicating that piR-823 detection may serve as a prognostic marker for GC." (PMID 39102033, 2025). "In summary, piR-823 acts as a tumor suppressor or promoter depending on the tumor type." (PMID 38303021, 2024). "In addition, lower expression of piR-57125 was associated with metastatic RCC, tumor recurrence and decreased overall survival." (PMID 38303021, 2024). "This functional assay reinforces our proposal that excessive expression of PIR may be a crucial event in tumorigenesis by conferring tumor cells resistance to immune clearance, suggesting that PIR is an emerging target for cancer immune therapy." (PMID 38148593, 2024). "piR-823 contained in EVs from peripheral blood of MM patients and cell lines plays an important role in cell–cell communication between endothelial and myeloma cells in the tumor microenvironment." (PMID 37568728, 2023).
tumor (continued). "In addition, the transwell assay results further indicated that suppressing piR-1742 expression facilitated the tumor cells’ migratory and invasive capacities, both of which were reduced by piR-1742 overexpression." (PMID 37332045, 2023). "Inhibition of piR-1742 significantly reduced tumor growth in RCC xenograft and organoid models." (PMID 37332045, 2023). "piR-36712 can be considered a novel tumor suppressor and a prognostic predictor of BC." (PMID 37568728, 2023). "Furthermore, elevated piR-823 levels significantly inhibited tumor growth in vivo in a dose-dependent manner." (PMID 38031146, 2023). "Moreover, Pirin signaling appears to have a critical role in tumor invasion and metastasis, as well as metabolic and neuro-pathological complications." (PMID 38033031, 2023). "Consistent with previous findings, PIR-TCR can suppress tumor growth." (PMID 37377887, 2023). "As a tumor suppressor, piR-36,712 suppresses the malignant phenotype." (PMID 38031146, 2023). "Together, our findings further support that piR-35127 and piR-46545 may function as tumor suppressors in lung cells, and down-regulation of piR-35127 and piR-46545 may contribute to lung cell transformation and tumorigenesis." (PMID 36826019, 2023). "Moreover, piR-017061 upregulation induces apoptosis of pancreatic cells and significantly reduces the tumor volume and weight in vivo." (PMID 38031146, 2023). "In addition, piR-162725 was significantly downregulated in the normal, untransformed cell line compared to both tumour cell lines (Log2 fold change = −15.04; adjusted p-value = 0.0091)." (PMID 36555927, 2022). "Using 18S as a reference gene and a 2-fold increase or a 50% decrease relative to normal tissue as a cut-off, we found that the mRNA levels for pirin were increased in 30/48 and decreased in 2/48 tumour samples in comparison with their corresponding matched normal tissues." (PMID 35204145, 2022). "piR-39980, which has been reported to have an oncogenic function in human osteosarcoma cells, has been found to have strong anti-tumor activity in fibrosarcoma (early metastatic lethal tumor) by repressing RRM2." (PMID 35755302, 2022). "Furthermore, we have demonstrated in mice xenograft models that treatment with piR-hsa-211106 agomir effectively suppressed tumor growth." (PMID 34249688, 2021). "Since piR-57125 is downregulated in ccRCC patients, we asked whether piR-57125 functions as a tumor suppressor in tumorigenesis." (PMID 34732692, 2021). "In the current study, we have identified piR-hsa-211106 as a tumor suppressor that is downregulated in LUAD and its underlying mechanism, providing evidence that piR-hsa-211106 has potential clinical value in the cancer development and treatment of LUAD patients." (PMID 34249688, 2021). "Previous studies had revealed that piR-32051, piR-39849, and piR-43607 were upregulated in ccRCC, whereas other piRNAs like piR-823, piR-38756, piR-57125, piR-34536, and piR51810 were downregulated in tumor tissues." (PMID 34790278, 2021). "In the present study, we also observed that direct injection of piR-hsa-211106 agomir into transplanted tumors in mice significantly inhibited tumor growth, indicating that piR-hsa-211106 agomir might be an effective drug for the treatment of LUAD." (PMID 34249688, 2021). "piR-30188 can act as a tumor suppressor through miR-367-3p regulation." (PMID 33673453, 2021). "Since miR-155 overexpression may inhibit tumor dissemination, extravasation, and colonization, Pirin may mediate, whether directly or indirectly, metastasis development." (PMID 33557375, 2021). "In summary, our study proposes that the activation of the EGFR/PI3K/AKT1/NRF2 pathway by HPV16 E7 leads to PIR/NF-κB activation in tumor oral epithelial cells, resulting in an increased cell migration, with the possibility remaining that this mechanism is involved in other epithelial cell models." (PMID 32679705, 2020).